INSM1 (INSM transcriptional repressor 1)
Diseases named in the same sentence as INSM1 in open-access papers (continued):
Sharing a sentence is not in itself a finding about the gene and the disease.
tumor (continued). "Several lines of evidence supported the idea that allelic differences in the Insm1 gene were responsible for the difference in tumor types, and that Insm1 is a suppressor gene of nonfunctioning PanNETs." (PMID 30796198, 2019). "In addition, identifying the direct transcriptional targets of INSM1 and its regulatory mechanisms in GBM may provide therapeutic opportunities for suppressing tumor growth, invasion, and recurrence." (PMID 41354838, 2025). "Subcutaneous transplant tumour tissues (H128-Mut, control), BPM tumour tissues, and LM tumour tissues were subjected to IHC analysis, which showed that H128-LM and H128-BPM still have the expression of neuroendocrine markers, including CD56, CHGA, SYP and INSM1 (P > 0.05)." (PMID 38644473, 2024). "Though INSM1 is a diagnostic marker for NETs of the thoracic cavity, there are other non-NET neoplasms of the thorax that may express INSM1." (PMID 34943408, 2021). "The tumor cells are immunostain positive for INSM1, SOX9, CD99 and S100, but negative for MUC4." (PMID 32164724, 2020). "The immune-histochemical profile of INSM1 in a cohort of peripheral neuroblastic tumors, using both tissue microarrays and whole-slide histologic sections, shows INSM1-positive staining in 78% of peripheral neuroblastic tumors and that no INSM1 signal was detected on the non-neuroblastic tumor." (PMID 36290282, 2022). "Immunohistochemical studies confirmed the diagnosis, with tumor cells positive for pancytokeratin, TTF1, synaptophysin, and INSM1, and negative for Napsin-A, p40, WT1, calretinin, and chromogranin." (PMID 40403473, 2025). "PROX1 was also highly expressed in a separate NEPC tumor cell population that was AR and KLK3 negative but positive for NEPC markers, including INSM1." (PMID 40454483, 2025). "Tumor cells tested negative for SMARCA4 but were positive for Chromogranin-A(CgA), Synaptophysin (SYN), Insm-1, TTF-1 (partial), and Ki67 (90%)." (PMID 40661782, 2025). "IHC analysis revealed that SYP is absent in all samples, whereas weak, focal CD56 and INSM1 positive staining was detected in both the patient lymph node metastatic biopsy and CU-PC01 PDX tumours." (PMID 38667288, 2024). "SMARCA4 expression was positively correlated with multiple NE genes including SYP, CHGA, INSM1, DLL3 and NCAM1 and negatively correlated with non-NE factors REST, NOTCH2, and YAP1 in both SCLC cell lines and patient tumor databases." (PMID 39080761, 2024). "Among other immunostains not shown, ATRX nuclear expression was retained in all tumor cells, and none of the tumor cells were positive for IDH1 R132H mutant protein, napsin, NKX3.1, CD45, synaptophysin, INSM1, SOX10 protein, p40, CDX2 protein, PSAP, or PSA." (PMID 38845695, 2024). "During the first round of immunohistochemical stains, the tumor cells showed positivity for CD56, CD99 (diffuse to patchy), INSM1, and NKX2.2, while they were negative for desmin, cytokeratin, SS18-SSX, and WT-1." (PMID 36765856, 2023). "In vivo, although reduction of CELSR3 did not impact NEPC tumor growth rate or metastatic potential, we did find that reduction of CELSR3 resulted in a diminution of NEPC markers (e.g., SYP, ASCL1, INSM1, SYP, and CHGA) in vitro and in vivo." (PMID 37546702, 2023). "The tumor was positive for CD117, Vim, CD56 and NSE and showed focal expression of desmin but was negative for myogenin, S-100, SYN, INSM1, CD34, STAT6, INI-1, Brachyury, ERG, TLE1, AE1/AE3, WT-1, CD99 and SMA." (PMID 35488288, 2022). "Immunohistochemically, the tumor cells were positive for CD117, vimentin, CD56 and NSE and focally expressed desmin; the cells were negative for myogenin, S-100, SYN, INSM1, CD34, STAT6, INI-1, Brachyury, ERG, TLE1, AE1/AE3, WT-1, CD99 and SMA." (PMID 35488288, 2022).
tumor (continued). "To investigate a potential LTF behavior of both TFs in NEPC, we performed SE analysis by H3K27ac profiling of ASCL1 and NEUROD1 NEPCs, and found that all models showed SE activation in common at a number of TFs (INSM1 and NFIB) regardless of the tumor subtype." (PMID 34599169, 2021). "ISL1, INSM1, and SECG all presented with exceedingly high PPVs concerning the distinction between NENs and non-NENs in the clinical setting, irrespective of WHO grade or tumor origin (primary tumor vs. metastasis)." (PMID 32813226, 2020). "Hence, a focally positive or positive ISL1, INSM1, and/or SECG staining (in > 30% of cells, which was the cut-off for focal positivity in the NEN group) is highly indicative of a NEN when the pathologist is facing a non-NEN tumor with a histological suspicion of a NEN." (PMID 32813226, 2020).
cancer (26 papers, 2017 to 2025). A tumor composed of atypical neoplastic, often pleomorphic cells that invade other tissues. "Insulinoma-associated protein 1 (INSM1) is a zinc-finger transcription factor implicated in the NE of cancer cells." (PMID 38673756, 2024). "Of note, INSM1 (insulinoma-associated 1) has been shown to be implicated in some cancers, and function as a transcriptional repressor." (PMID 32093041, 2020). "We also found that retinoic acid, a compound known to promote cell differentiation, reduces INSM1 and another cancer-driving gene, N-Myc." (PMID 41514864, 2025). "We found that INSM1 shows consistently high accuracy, especially in terms of ruling out other cancer types." (PMID 40805240, 2025). "Immunohistochemically, the hepatic lesion exhibited diffuse vimentin positivity, partial Cam5.2, and scattered INSM-1 expression, suggesting a mesenchymal transition of the carcinoma with partial neuroendocrine differentiation." (PMID 40989881, 2025). "Other genes include immune responses of T cells in cancer cells, insulin-receptor-related protein (INSRR), MHC II complex HLA-DQB and HLA-DQA, IL-12A, IL-20, glucose transporter 4 (GLUT4), insulinoma-associated protein 1 (INSM1), and insulin receptor (INSR)." (PMID 36769056, 2023). "It is noteworthy that both tumor types can focally express neuroendocrine markers (synaptophysin, chromogranin, and INSM1) in most SMARCA4-deficient carcinomas and up to 18% of SMARCB1-deficient carcinomas." (PMID 36941503, 2023). "Our INSM1 promoter-driven luciferase screening-platform will be a valuable approach to screening additional novel small-molecules for NB cancer therapy." (PMID 36290282, 2022). "In the current review article, we discuss the essential role of INSM1 and N-Myc interplay in aggressive NB as potential targets for NB cancer therapy." (PMID 36290282, 2022). "The genes assayed were neuroendocrine-associated genes (INSM1, ASCL1, NRCAM, and SNAP25), one gene centered in the gene regulatory network (NUF2), and five possibly cancer-associated genes (PTP4A3, RFC4, REST, APEH, and FBLN2)." (PMID 34395507, 2021). "In eight large cell NE carcinomas or carcinomas with large cell components, INSM1 showed similar sensitivity (6/8) to SNY (7/8), CgA (6/8) and CD56 (6/8)." (PMID 34943408, 2021). "We aimed to understand how INSM1 contributes to cancer’s aggressiveness and poor differentiation." (PMID 41514864, 2025). "Disrupting this cycle alters INSM1 activity and may help push cancer cells toward normal development." (PMID 41514864, 2025). "Specific INSM1 expression is tightly controlled by INSM1 proximal promoter sequence (−426/+40 bp), which demonstrated specific expressions of reporter gene (LacZ or thymidine kinase, tk) in either transgenic animal model or cancer gene therapy experiment." (PMID 37627018, 2023). "INSM1 had the highest positivity and was seen in all 11 carcinomas." (PMID 37082801, 2023). "The gene signature with strong invasive potential was enriched in 'Pathways in cancers' and 'MAPK pathway', with significantly higher in situ INSM1 and HSPA2 protein expression in invasive NF-PitNEts." (PMID 33391466, 2021). "We next looked at the relative expression of INSM1 and YAP1 among all cancer cell lines in the CCLE." (PMID 29088741, 2017). "This revealed that INSM1 was strongly positive (100%) for the pure NET and the NET component of MiNEN, and was negative for the adenocarcinoma component (as seen with other GI-tract pure carcinomas)." (PMID 34943408, 2021). "Additional INSM1 mRNA expression levels in a range of neurological cancers with NE features and other non-NE cancers were analyzed from the available datasets in an R2 Genomics Analysis and Visualization Platform (http//r2.amc.nl, accessed on 21 February 2022)." (PMID 36290282, 2022). "Non-NETs like carcinomas, such as colorectal adenocarcinoma, almost always were negative for INSM1." (PMID 34943408, 2021).
cancer (continued). "ASCL1 KO tumors developed a poorly differentiated carcinoma without detectable expression of the NE lineage markers SYP, INSM1, or DLL3 but showed higher expression of NOTCH2, HES1, and KRT8." (PMID 39024561, 2024).
adenocarcinoma (9 papers, 2021 to 2026). A common cancer characterized by the presence of malignant glandular cells. "MYCL expression strongly correlates with the neuroendocrine lineage regulators ASCL1 and INSM1 and inversely with adenocarcinoma-associated genes." (PMID 42001796, 2026). "Interestingly, some of the Hmmr-positive adenocarcinoma cells were also positive for Ascl1 and Insm1 suggesting that this subpopulation of adenocarcinoma cells may have overlapping features or may be in the process of transitioning toward the NEPC phenotype." (PMID 37546702, 2023). "The CDH1+/EPCAM+ epithelial cells were enriched in adenocarcinoma and adenosquamous tissues but rarely noticed in NET, in which the EPCAM+/INSM1+ neuroendocrine cells were exclusively identified." (PMID 34185421, 2021). "To further confirm whether the NEPC and adenocarcinoma markers are expressed in distinct cells, we performed immunofluorescence to costain for the neuroendocrine markers SYP and INSM1 along with the epithelial marker CK8." (PMID 37546702, 2023). "Immunohistochemically, the NEC cells were diffusely positive for synaptophysin, with focal expressions of INSM1, chromogranin A and NCAM, whereas the adenocarcinoma cells were mostly negative for these NE markers." (PMID 35801304, 2022).
infection (4 papers, 2011 to 2023). The state of being infected such as from the introduction of a foreign agent such as serum, vaccine, antigenic substance or organism. "Numerous transcription factors are also induced or upregulated by infection including insulinoma-associated 1 (Insm1)." (PMID 24086132, 2013). "Using these expression vectors, we observed that INSM1 expression enhanced ICP0 expression early in infection." (PMID 21609490, 2011). "Our microarray analysis showed that the level of INSM1 mRNAs increased by at least 400-fold 9 h after infection in HSV-infected cells compared with mock-infected cells." (PMID 21609490, 2011). "INSM1 gene expression in HSV-1-infected normal human epidermal keratinocytes increased at least 400-fold 9 h after infection; INSM1 promoter activity was also markedly stimulated." (PMID 21609490, 2011). "Subcellular localization of ICP0 was markedly affected by INSM1 overexpression late in infection." (PMID 21609490, 2011). "In HSV-1-infected cells, INSM1-FL localized to the replication compartment late in infection." (PMID 21609490, 2011). "In INSM1-FL-expressing cells, however, ICP0 remained in the nucleus, indicating that INSM1 can inhibit the translocation of ICP0 to the cytoplasm late in infection." (PMID 21609490, 2011). "Thus, HEp-2 cells were transfected with empty and INSM1-FL vectors, infected with HSV-1(F) 48 h after transfection, fixed with formaldehyde 7 h after infection, and processed for ChIP assays." (PMID 21609490, 2011). "In addition, we employed an INSM1 promoter-driven luciferase expression vector to confirm that INSM1 promoter activity was markedly elevated by infection with HSV and not with UV-inactivated HSV, strongly suggesting that HSV gene expression is necessary for activating the INSM1 promoter." (PMID 21609490, 2011).
head and neck tumors (3 papers, 2019 to 2025). "Our experience confirms a high prevalence of INSM1 positivity in laryngeal and pharyngeal NECs which corroborates previous findings that proposed its use as a first-line and stand-alone marker of neuroendocrine differentiation for head and neck tumors." (PMID 34638312, 2021).
gastrointestinal tumors (2 papers, 2021 to 2023). "Recently, INSM1 has emerged as an additional general neuroendocrine marker because it was shown to have better diagnostic ability than synaptophysin and chromogranin A in gastrointestinal tumors." (PMID 37027114, 2023). "INSM1 and NEUROG3 are essential markers for pancreatic neuroendocrine tumours and have been implicated in gastrointestinal tumours, diarrhoea, and malabsorption." (PMID 33436826, 2021).
INSM1 also shares sentences with these, for which no sentence is quoted: acinar cell carcinoma (3 papers); alveolar rhabdomyosarcoma (2); lung (2); melanoma (2); mucoepidermoid carcinoma (2); pituitary adenomas (2); skin cancer (2); Alpha-thalassemia (1); astrocytomas (1); B-Cell Lymphoma (1); central nervous system neoplasm (1); cervical carcinoma (1); chronic lymphocytic leukemia (1); colorectal adenocarcinoma (1); ductal adenocarcinoma (1); epilepsy (1); Ewing sarcoma (1); extraskeletal myxoid chondrosarcoma (1); Gliomas (1); glioneuronal tumours (1); goblet cell adenocarcinomas (1); hepatocellular carcinoma (1); large cell neuroendocrine carcinoma of the breast (1); lung adenocarcinoma (1); lymphoid tumors (1); mantle cell lymphoma (1); medulloblastoma (1); mesothelioma (1); metabolic syndrome (1); non-small cell lung carcinoma (1).
A further 13 diseases each share a sentence with INSM1 in 1 paper.